WNK1 (WNK lysine deficient protein kinase 1)
Diseases named in the same sentence as WNK1 in open-access papers (continued):
Sharing a sentence is not in itself a finding about the gene and the disease.
heart failure (2 papers, 2020 to 2024). Inability of the heart to pump blood at an adequate rate to meet tissue metabolic requirements. "In vivo testing of senolytic, WNK1 inhibitor, and anti-syncytia drug implicated senescence syncytia as a central driver in promoting heart failure progression, highlighting the clinical potential of WNK1 inhibitors as a novel interventional therapeutic strategy." (PMID 39102426, 2024). "WNK1 may be a druggable target in the management of heart failure associated with long COVID-19." (PMID 39102426, 2024). "In pre-existing heart failure mice, the WNK1 inhibitor WNK463, anti-syncytial drug niclosamide, and senolytic dasatinib protect the heart from exacerbated heart failure triggered by SARS-2-S." (PMID 39102426, 2024). "We found that WNK1 inhibition alleviated SARS-2-S-aggravated heart failure and reduced serum cTnT and IL-1β levels." (PMID 39102426, 2024). "We then wanted to test if WNK1 inhibition by WNK463 can alleviate heart failure exacerbated by SARS-2-S through rescuing metabolic dysfunction." (PMID 39102426, 2024). "SARS-2-S exacerbated heart failure progression, a phenotype that could be largely rescued by WNK1 inhibitors, anti-syncytial drugs or senolytic agents." (PMID 39102426, 2024). "Therefore, WNK1 intervention can effectively protect the heart from exacerbated heart failure triggered by SARS-2-S." (PMID 39102426, 2024). "Importantly, SARS-2-S-exacerbated heart failure could be largely rescued by WNK1 inhibitor, anti-syncytial drug or senolytic agent." (PMID 39102426, 2024).
Hyperchloremia (2 papers, 2018 to 2024). An abnormally increased chloride concentration in the blood. "Functional enrichment analysis revealed that oral poisoning owing hyperchloremia is associated with 4 proteins e.g. Kelch-like protein 3, Serine/threonine-protein kinase WNK4, Serine/threonine-protein kinase WNK1 and Cullin-3." (PMID 38615119, 2024).
Insulin resistance (2 papers, 2018 to 2022). Increased resistance towards insulin, that is, diminished effectiveness of insulin in reducing blood glucose levels. "Of note, we observed insulin resistance and decreased WNK1 phosphorylation in T2D db/db mice as compared to the control mice." (PMID 30410865, 2018). "In addition, compared with control mice, T2D db/db mice exhibit significant insulin resistance and decreased WNK1 phosphorylation." (PMID 30410865, 2018). "Subsequently, we examined insulin resistance and WNK1 signaling in db/db mice skeletal muscle." (PMID 30410865, 2018).
liver cancer (2 papers, 2022 to 2025). An epithelial or non-epithelial malignant neoplasm that arises from the liver. "Xenotransplantation might result in different liver cancer formation to that which occurs in reality, and WNK1 has been found to act as an oncogene in many cancers." (PMID 36292952, 2022).
multiple myeloma (2 papers, 2023 to 2025). "It has been found that the overexpression of Akt leads to the increase of WNK1 protein phosphorylation in the bone marrow microenvironment of multiple myeloma cells." (PMID 37652923, 2023).
ovarian carcinoma (2 papers, 2023 to 2025). A malignant neoplasm originating from the surface ovarian epithelium. "Given the significant overexpression of WNK1 in ovarian cancer, we proceeded to investigate the impact of WNK1 on ovarian cancer cell biological behavior." (PMID 40510161, 2025). "The current study developed a predictive model of CSOARG for prognosis in ovarian cancer using eight key genes (WNK1, ANGPTL4, AREG, IGF1, CXCL10, GMPR, FANCB, LYG1)." (PMID 40510161, 2025). "A hub gene WNK1 was validated and acted as an oncogene affecting ovarian cancer cell viability and migration." (PMID 40510161, 2025). "The cell viability of ovarian cancer cells after the knockdown of WNK1 was decreased compared to the control group at 24, 48, and 72 h." (PMID 40510161, 2025). "The present study uncovers the involvement of WNK1 in ovarian cancer pathophysiology upstream of the MEK5–ERK5 MAPK route and shows the potential therapeutic value of the targeting of this route in that disease." (PMID 37029785, 2023). "Mechanistically, we demonstrate that WNK1 exerted its action through the MEK5–ERK5 signalling module in ovarian cancer." (PMID 37029785, 2023). "The genetic and pharmacological studies performed pointed to an implication of WNK1 in the control of proliferation of ovarian cancer cells." (PMID 37029785, 2023). "We identified WNK1 as a highly phosphorylated protein in ovarian cancer and found that its activation or high expression had a negative impact on patients’ survival." (PMID 37029785, 2023). "Western blotting analyses confirmed the expression of pWNK1 and WNK1 in the four ovarian cancer cell lines." (PMID 37029785, 2023). "Furthermore, WNK1 has a pathophysiological role and influences the efficacy of trametinib in ovarian cancer." (PMID 40510161, 2025). "It has also been shown that WNK1 increased cisplatin resistance in ovarian cancer cells." (PMID 40510161, 2025). "We found that the knockdown of WNK1 inhibited ovarian cancer cell migration." (PMID 40510161, 2025). "Of note, a substantial number of ovarian cancer patients (around 12%) have amplification of WNK1 and the evaluation of this gene could be used as biomarker for patient selection." (PMID 37029785, 2023). "Phosphorylation of WNK1 was detected in both patient samples and ovarian cancer cell lines." (PMID 37029785, 2023). "All the ovarian cancer cell lines expressed the WNK1 downstream kinases MEKK2, MEK5 and ERK5." (PMID 37029785, 2023). "The levels of WNK1 and pWNK1 were also analysed in a cohort of 57 patients with ovarian cancer." (PMID 37029785, 2023). "Moreover, in silico analyses in ovarian cancer patients collected from public databases, showed that high expression of WNK1 correlated with poor outcome." (PMID 37029785, 2023). "Furthermore, downregulation of the WNK1 downstream kinases MEKK2, MEK5 and ERK5 caused a reduction in proliferation of ovarian cancer cells." (PMID 37029785, 2023). "Moreover, in different experimental settings, including an ex vivo patient‐derived model consisting of ovarian cancer cells cultured with autologous patient sera, we show that inhibition of WNK1 or MEK5 increased the anti‐proliferative and anti‐tumour efficacy of trametinib." (PMID 37029785, 2023). "The finding that the activation status of WNK1 and ERK1/2 predicts a poor outcome in ovarian cancer, prompted us to explore their connection in this disease." (PMID 37029785, 2023). "Further, qPCR and Western blot revealed that WNK1 was highly expressed in A2780 and OVCAR-3 ovarian cancer cells in comparison to IOSE-80 non-cancerous cells." (PMID 40510161, 2025).
pancreatitis (2 papers, 2014 to 2021). Inflammation of the pancreas. "We hypothesized that CFTR variants that disrupt the WNK1-SPAK-associated increase in bicarbonate permeability will increase the risk of pancreatitis and affect other organs in which CFTR is used for bicarbonate secretion." (PMID 25033378, 2014). "To better understand the location and structural effects of the nine amino acid variants conferring risk of pancreatitis and causing dysfunction of the electrophysiological response to WNK1-SPAK activation, we developed structural models of CFTR and conducted dynamic simulations." (PMID 25033378, 2014).
Polyuria (2 papers, 2023 to 2025). An increased rate of urine production. "Neuron-specific conditional KO (cKO) of Wnk1 caused polyuria with decreased urine osmolality that persisted in water restriction and blunted water restriction–induced AVP release." (PMID 37071482, 2023).
pulmonary arterial hypertension (2 papers, 2021 to 2024). Pulmonary arterial hypertension (PAH) is a group of diseases characterized by mean pulmonary artery pressure >20 mmHg and elevated pulmonary arterial resistance leading to right heart failure. "Hypochloremia, a condition of predicted WNK1 activation in patients with pulmonary arterial hypertension, is associated with more severe RV dysfunction." (PMID 34869947, 2021). "Previous studies have shown that small-molecule inhibition of WNK1 prevents the downregulation of mitochondrial metabolism and improves RV function and survival in pulmonary arterial hypertension." (PMID 39102426, 2024).
retinoblastoma (2 papers, 2018 to 2021). A malignant tumor that originates in the nuclear layer of the retina. "Pertaining to its role in angiogenesis, WNK1 can be a probable therapeutic target for retinoblastoma." (PMID 29914080, 2018). "In our study, WNK1 was identified to be hyperphosphorylated in retinoblastoma." (PMID 29914080, 2018). "The substrates of WNK1 such as MAPK1, OXSR1, STK39 (SPAK), and ANKS1A were identified to be phosphorylated in our study, but their phosphorylation status was unchanged in retinoblastoma compared to control retina tissues." (PMID 29914080, 2018).
adenomyosis (1 paper, 2020). The growth of endometrial tissue inside the muscular wall of the uterine corpus. "Examination of uterine cross sections from older mice (26 and 50 weeks) further demonstrated invasion of glands into the myometrium, suggesting that WNK1 ablation caused adenomyosis-like features." (PMID 33048843, 2020). "In this study, we explored this further by examining the in vivo function of WNK1, and we demonstrate here that loss of WNK1 led to hyperplasia, adenomyosis-like features, and impaired implantation." (PMID 33048843, 2020).
Alkalosis (1 paper, 2018). Depletion of acid or accumulation base in the body fluids. "We show that WNK1+/FHHT:SPAK243A/243A mice display an intermediate phenotype, between that of control and SPAK243A/243A mice, with normal blood pressure but hypochloremic metabolic alkalosis." (PMID 29459793, 2018).
Autoimmunity (1 paper, 2025). The occurrence of an immune reaction against the organism's own cells or tissues. "Given our previous work demonstrating the importance of WNK1 for homeostatic efferocytosis in vitro, we sought to determine if TRM-specific genetic perturbation of WNK1 results in autoimmunity or inflammatory disease." (PMID 40436823, 2025).
autonomic disorder (1 paper, 2016). "Except the autonomic disorder, her neurological examination had almost the same clinical features as those of previous patients with HSAN type II with WNK1/HSN2 gene mutations." (PMID 27765018, 2016). "Although an autonomic disorder has never been reported in HSAN type II with the WNK1/HSN2 gene mutation, our patient presented with several symptoms of autonomic disturbances." (PMID 27765018, 2016).
autonomic neuropathy (1 paper, 2022). An inherited or acquired peripheral neuropathy affecting the autonomic nervous system. "The aberration of WNK1 led to hereditary sensory and autonomic neuropathy in humans." (PMID 35924220, 2022).
blood pressure (1 paper, 2009). "On the other hand, heterozygous knockout mice have low blood pressure, and this is associated with decreased WNK1 expression at the mRNA and protein level." (PMID 19347040, 2009).
Central diabetes insipidus (1 paper, 2025). A form of diabetes insipidus related to a failure of vasopressin (AVP) release from the hypothalamus. "Mice deleted of Wnk1 in the CVOs exhibit impaired hypertonicity‐induced AVP release and phenotypes of central diabetes insipidus." (PMID 41246868, 2025).
cervical cancer (1 paper, 2018). A primary or metastatic malignant neoplasm involving the cervix. "In terms of the obtained results, the hub proteins KAT2B, PARP1, CDK1, GSK3B, WNK1, and CRYAB have been associated with several cancers in previous studies, but their association with cervical cancer is proposed here for the first time." (PMID 30020984, 2018). "Furthermore, the KAT2B, PARP1, CDK1, GSK3B, WNK1, and CRYAB, proteins are associated with various cancer types, but their roles in cervical cancer have not been identified." (PMID 30020984, 2018).
clear cell renal cell carcinoma (1 paper, 2025). "It has been shown that WNK1 activates NFAT transcription factors and promotes cell migration in clear cell renal cell carcinoma (ccRCC)." (PMID 40510161, 2025).
colon cancer (1 paper, 2022). "A recent study demonstrated elevated expression of miR-524 in colon cancer, which inhibited angiogenesis through WNK1." (PMID 35193488, 2022).
developmental arrest (1 paper, 2020). "Thus, WNK1 deficiency causes changes in several key biochemical pathways, any or all of which could be causing the developmental arrest." (PMID 33051000, 2020).
Failure to thrive (1 paper, 2025). Failure to thrive (FTT) refers to a child whose physical growth is substantially below the norm. "Unexpectedly, mice with Csf1r promoter-driven Cre-mediated deletion of Wnk1 (WNK1-deficient) exhibited failure to thrive and were unable to live beyond four weeks of age." (PMID 40436823, 2025).
fungal infection (1 paper, 2014). "Furthermore, whether acs-3 or nhr-25 act with genes that regulate antimicrobial peptide expression specifically in response to fungal infection and epidermal damage (sta-2, snf-12, nipi-3, dapk-1), and osmotic stress (wnk-1-gck-3 signaling) needs to be determined." (PMID 24651852, 2014).
gout (1 paper, 2021). A condition characterized by painful swelling of the joints, which is caused by deposition of urate crystals. "This suggests an important link between treating blood pressure by targeting the WNK1 pathway and increasing the risk of exaggerating NLRP3-mediated inflammatory diseases such as gout." (PMID 34315884, 2021). "Since loop and thiazide diuretics inhibit downstream WNK1 signaling events by blocking cation-Cl− co-transporters, it is likely that these two events play important roles in the severity of gout in patients taking diuretics." (PMID 34315884, 2021).
head and neck cancer (1 paper, 2024). A primary or metastatic malignant neoplasm affecting the head and neck. "Because WNK1 regulates cell migration and β-catenin signaling also promotes metastasis in head and neck cancer, wound healing assays were performed with sublethal doses of PV-10 to investigate its effect on migration of aggressive head and neck cancer cells." (PMID 38672602, 2024).
herpes infections (1 paper, 2013). "During herpes infections, many genes involved in metabolism like oat or fasn are under expressed, whereas others, like dbI and wnk1, are overexpressed, suggesting a disruption in host metabolic activity." (PMID 23987141, 2013).
ischemia (1 paper, 2022). A hypoperfusion of the BLOOD through an organ or tissue caused by a PATHOLOGIC CONSTRICTION or obstruction of its BLOOD VESSELS, or an absence of BLOOD CIRCULATION. "For example, loss of WNK3 may reduce ischemia-associated brain damage, whereas mutations in WNK1 and WNK4 disrupt renal salt uptake to induce pseudohypoaldosteronism type II (PHAII)." (PMID 35179207, 2022).
kidney cancer (1 paper, 2021). Primary or metastatic malignant neoplasm involving the kidney. "In particular, ELF5, SLC17A3, RALBP1, WNK1, APOC1, and CRYAB were experimentally verified to play an important role in the occurrence and development of kidney cancer." (PMID 34445498, 2021).
neuroblastoma (1 paper, 2022). Neuroblastoma (NB) is the most common solid, extracranial childhood tumor. "We have previously reported that WNK1 and WNK4 are involved in induction of neural marker genes and neurite elongation in mouse neuroblastoma Neuro2A cells." (PMID 36151370, 2022).
osteoporosis (1 paper, 2024). A condition of reduced bone mass, with decreased cortical thickness and a decrease in the number and size of the trabeculae of cancellous bone (but normal chemical composition), resulting in increased fracture incidence. "CYLD mitigates NLRP3 inflammasome-triggered pyroptosis in osteoporosis through its deubiquitination of WNK1." (PMID 38561786, 2024).
ovarian serous cystadenocarcinoma (1 paper, 2023). A malignant serous cystic epithelial neoplasm arising from the ovary. "Analysis of the Ovarian Serous Cystadenocarcinoma dataset (TCGA, n = 579) revealed that chromosomal cytoband 12p13.33, which comprises the WNK1 gene, was among the top‐ranked altered genomic locations, reaching statistical significance (p = 8.7e−07)." (PMID 37029785, 2023).
ovarian tumours (1 paper, 2023). "Genomic analyses showed amplification of WNK1 in human ovarian tumours." (PMID 37029785, 2023).
periodontitis (1 paper, 2024). An acute or chronic inflammatory process that affects the tissues that surround and support the teeth. "The integration of GWAS with the eQTLs of these genes from the peripheral blood prioritized 6 genes, including MCUR1, RAP2A, FOS, PANX1, NFIX and WNK1, in the pathogenesis of periodontitis-related T2D." (PMID 38811930, 2024). "Furthermore, MCUR1, RAP2A, FOS, PANX1, NFIX and WNK1 were verified to play important roles in the pathogenesis of periodontitis-related T2D, shedding light on the discovery of potential drug targets for periodontitis patients to prevent T2D." (PMID 38811930, 2024). "MCUR1, RAP2A, FOS, PANX1, NFIX and WNK1 may play important roles in the pathogenesis of periodontitis-related T2D, shedding light on the development of potential drug targets." (PMID 38811930, 2024). "The integration of GWAS with the expression quantitative trait locis of these genes from the peripheral blood genetically prioritized 6 candidate genes, including 2 risk genes (RAP2A, MCUR1) and 4 protective genes (WNK1, NFIX, FOS, PANX1) in periodontitis-related T2D." (PMID 38811930, 2024).
small cell lung carcinoma (1 paper, 2017). Small cell lung cancer (SCLC) is a highly aggressive malignant neoplasm, accounting for 10-15% of lung cancer cases, characterized byrapid growth, and early metastasis. "Our results reveal that knockdown of WNK1 decreases SPARC treatment-induced migration and reverses the transition of the mesenchymal phenotype in non-small cell lung cancer cell lines H1299 and CL1-5." (PMID 28969021, 2017).
sterility (1 paper, 2020). "Taken together, these results illustrated compromised ability to support pregnancy and premature sterility with uterine loss of WNK1." (PMID 33048843, 2020).
tobacco use disorder (1 paper, 2020). "Functional analysis showed the association of three genes (CDS2, TBC1D22A and WNK1) with tobacco use disorder." (PMID 32344947, 2020). "Three genes: CDS2, TBC1D22A, and WNK1 were connected to tobacco use disorder, which may be caused by the prevalence of smoking in 14.7% of CVD population (control group consists of non-smoking individuals)." (PMID 32344947, 2020).